FADS2 (fatty acid desaturase 2)
Diseases named in the same sentence as FADS2 in open-access papers (continued):
Sharing a sentence is not in itself a finding about the gene and the disease.
lymphoma (1 paper, 2025). A malignant (clonal) proliferation of B- lymphocytes or T- lymphocytes which involves the lymph nodes, bone marrow and/or extranodal sites. "Future studies could identify such metabolic pathways to target alongside SCD1 and FADS2 in EBV-associated lymphomas." (PMID 40403013, 2025). "Future studies would need to establish preclinical models of EBV-associated lymphomas to further validate this approach and demonstrate that the in vitro effects of dual SCD1 and FADS2 inhibition on cell growth translate to in vivo models." (PMID 40403013, 2025). "However, the significantly higher expression of both SCD1 and FADS2 in EBV-immortalized LCLs still positions these desaturases as viable therapeutic targets against EBV-driven lymphomas." (PMID 40403013, 2025). "Finally, our study assessed whether the effects of SCD1 and FADS2 perturbation observed in vitro in EBV-immortalized LCLs held true in tumor-derived models of EBV+ lymphomas, thereby pointing to potential therapeutic applications." (PMID 40403013, 2025).
magnesium deficiency (1 paper, 2025). A nutritional condition produced by a deficiency of magnesium in the diet, characterized by anorexia, nausea, vomiting, lethargy, and weakness. "Impaired D6D activity (genetic FADS2 variants, zinc/magnesium deficiency, chronic inflammation, or LA overload) limits GLA/DGLA formation and may shunt LA toward pro-inflammatory AA-derived mediators." (PMID 41441285, 2025).
mastitis (1 paper, 2020). Inflammation of breast tissue during lactation or postpartum due to an obstructed duct or infection. "Our results provided direct evidence that FADS2 was an interesting candidate for selection to increase milk production and improve resistance against mastitis." (PMID 32290630, 2020). "Our results demonstrated that FADS2 was an interesting candidate for selection to increase milk production and improve resistance against mastitis." (PMID 32290630, 2020).
metastatic tumors (1 paper, 2022). "QPCR analysis generally showed that relatively higher mRNA levels of SCD1 and FADS2 were detected in samples of omental metastatic tumors than in the respective primary tumors (n = 10 pairs)." (PMID 35547771, 2022). "Western blot analysis showed that the expression levels of SCD1, FADS2, GPX4, and TFR1 in omental metastatic tumors were relatively higher than their counterpart primary tumor tissues." (PMID 35547771, 2022).
mood disorder (1 paper, 2023). A cognitive disorder a disturbance in which the person's mood is hypothesized to be the main underlying feature. "These enzymes (FADS1 and FADS2) are involved in the metabolism of eicosapentaenoic acid (EPA) and docosahexaenoic acid (DHA), which are thought to potentially benefit patients with mood disorders." (PMID 36806390, 2023).
myeloma (1 paper, 2020). "Like our data from analysis of normal donor versus myeloma patient MSCs, we again found that Fads1 and Fads2 were significantly downregulated in MM-3T3-L1s compared to controls." (PMID 33680918, 2020).
myopia (1 paper, 2025). "Summary data‐based Mendelian randomization (SMR) and colocalization analysis were conducted to examine the associations between the FADS1 and FADS2 genes and three traits of myopia in European populations." (PMID 40792044, 2025). "We further conducted colocalization analysis of FASD1 and FADS2 from both blood and retinal tissue and the three traits of myopia." (PMID 40792044, 2025).
nephrotic syndrome (1 paper, 2025). A collection of symptoms that include severe edema, proteinuria, and hypoalbuminemia; it is indicative of renal dysfunction. "In the Nephrotic Syndrome Study Network (NEPTUNE) database, LPCAT3, ELOVL7 and FADS2 were all negatively associated with eGFR and positively associated with creatine and urea nitrogen." (PMID 41285716, 2025).
ovarian dysfunction (1 paper, 2023). The inability of the ovaries to function. "Among the genes we identified through coexpression of three datasets, PNPLA3, MVD, MMP9, oncostatin M (OSM), LCK, triggering receptor expressed on myeloid cells 1 (TREM1), FADS2, proprotein convertase subtilisin/kexin type 9 (PCSK9), and C3 are involved in lipid metabolism and ovarian dysfunction." (PMID 37537636, 2023).
peripheral artery disease (1 paper, 2019). "We found an association of FADS2 rs28456-G with peripheral artery disease (P = 2.2 × 10−4) and aterial embolism and thrombosis (P = 2.5 × 10−4)." (PMID 31551469, 2019).
retinal disease (1 paper, 2017). "Three genes had SNP associations to retinal disease: Ldlrad3, Fads2, and Fbln7." (PMID 29116131, 2017).
Sepsis (1 paper, 2023). Sepsis is defined as life-threatening organ dysfunction caused by a dysregulated host response to infection. "Notably, these DEPs including Fads2, Fgb, Cypla2, Cyp2e1, Cfb, Serping1, Fgg, Etnppl, Agt, Hsd3b5, Gnmt, A2m, Pck1, Stat3, Ptpn1, Scd1, Slc2a1, and Uox were key genes in liver sepsis, which maybe associated with inflammation in sepsis." (PMID 37255592, 2023).
skin melanoma (1 paper, 2023). "What's more, FADS2 expression was positively related to proliferation, cell cycle, DNA damage, and DNA repair response in skin melanoma." (PMID 36788618, 2023). "By contrast, FADS2 expression was negatively related to inflammation, quiescence, and differentiation in skin melanoma." (PMID 36788618, 2023).
cancer (73 papers, 2011 to 2026). A tumor composed of atypical neoplastic, often pleomorphic cells that invade other tissues. "Dietary supplementation of omega-3 fatty acids, along with genetic variants in the FADS1/FADS2 gene clusters, in cancer patients." (PMID 40430008, 2025). "Based on multivariate analysis, SCD or FADS2 was identified as a prognostic risk factor for 33 types of cancer, especially BRCA." (PMID 38905386, 2024). "FADS2 expression was also noted to be positively linked to cancer-associated fibroblast (CAFs) infiltration in many cancers." (PMID 36788618, 2023). "High FADS2 expression was linked to the advanced pathological stage and histological grade across various cancers." (PMID 36788618, 2023). "Especially, FADS2 expression positively correlated with cancer-associated fibroblast (CAFs) infiltration." (PMID 36788618, 2023). "Scd, Scd2, Dgat2, Fads2, Lpin1, Gpat3, Acaa2, Lpcat3, Pcyt2 and Pla2g4a have been reported to be closely associated with cancer." (PMID 35122680, 2022). "The loss of FADS2-encoded activities in cancer cells shuts down normal PUFA biosynthesis, deleting the endogenous supply of eicosanoid and downstream docosanoid precursors, and replacing them with unusual butylene-interrupted fatty acids." (PMID 22140540, 2011). "PUFA status in plasma/tissues and its association with FADS1/FADS2 polymorphism in cancer patients." (PMID 40430008, 2025). "Moreover, according to available data, FADS1 is causally involved in cancer cell proliferation and, together with FADS2, has emerged as a promising pharmacological target for anti-cancer therapy." (PMID 40430008, 2025). "PUFA status and FADS1/FADS2 genotypes as potential risk factors for cancer development." (PMID 40430008, 2025). "Since the data on PUFA metabolism and FADS polymorphisms remain inconclusive, this review aimed to examine the influence of FADS1 and FADS2 gene variants on metabolism and biological effects of omega-3 fatty acids and gamma-linolenic acid, both individually and in combination, in cancer patients." (PMID 40430008, 2025). "Thus, we next investigated whether FADS2 over expression was associated with clinicopathological parameters and prognosis at the pan-cancer level." (PMID 36788618, 2023). "In recent studies, FADS2 acted noncanonically to convert the SCD1 substrate palmitate to sapienate in SCD1-independent cancer cells, highlighting the highly plastic nature of FADS2 and identifying a critical interplay between SCD1 and FADS2 in tumor biology." (PMID 40403013, 2025). "This review aimed to investigate the relationship between FADS1 and FADS2 gene variants and dietary intake, supplementation, or intervention with omega-3 fatty acids, gamma-linolenic acid (GLA), or their combination in cancer patients." (PMID 40430008, 2025). "While genetic variations in the FADS1 and FADS2 genes are linked to PUFA metabolism and cancer risk, the interplay between dietary PUFA intake and genetic factors remains insufficiently understood." (PMID 40430008, 2025). "This was accompanied by the upregulation of key enzymes involved in synthesis (FASN), elongation (ELOVL1,2,5,6,and 7), and desaturation (FADS1 and FADS2) in ovarian tissue compared to NC groups, implicating these pathways in cancer progression." (PMID 40371224, 2025). "Remarkably, UA enhances susceptibility to ferroptosis by impeding the SLC7A11/GSH/GPX4 Axis and suppressing the fatty acid desaturase FADS2, suggesting promising prospects for UA's clinical utility in cancer treatment." (PMID 40535804, 2025). "SCD and FADS2 are pivotal enzymes within the fatty acid desaturation pathway and are markedly expressed in various cancer types." (PMID 40535804, 2025). "Recent evidence suggests that, besides SCD enzymes, FADS2 also plays a role in FA desaturation, and cancer cells utilize a FADS2-dependent alternative pathway to transfer palmitate to sapienate to support cell proliferation." (PMID 40814339, 2025).
cancer (continued). "In this context, FADS2 emerges as a promising target for therapeutic intervention in cancer treatment." (PMID 40535804, 2025). "The University of Alabama at Birmingham cancer data analysis portal database indicates that the expression and methylation levels of SCD or FADS2 are associated with various clinicopathological factors in patients with BRCA." (PMID 38905386, 2024). "Conversely, the down-regulated DEGs are linked to pathways associated with cancer or immune responses, in alignment with previous findings, such as SCD1, ELOV2, FADS1, FADS2, and BMP6." (PMID 38693536, 2024). "Zeb1-binding regions were associated with an active, open (FADS2) or inactive, closed (SCD and FASN) chromatin state in Zeb1high-expressing cancer cells, and an inverse pattern in Zeb1-depleted cells." (PMID 39009641, 2024). "Pharmacological inhibition of selected lipogenic enzymes (SCD and FADS2) allows the manipulation of ferroptosis sensitivity preferentially in high-Zeb1-expressing cancer cells." (PMID 39009641, 2024). "FADS2 expression is prognostic in some cancers, and FADS2-mediated sapienate metabolism is regulated by mTOR signaling." (PMID 39337514, 2024). "Meanwhile, the FADS2 expression level was mainly upregulated in malignant tumor cells, epithelial cells, mast cells, and macrophages, whereas it was extremely low in CD4 Tconv cells, Treg cells, plasma cells, and neutrophils." (PMID 38905386, 2024). "The prognostic ability of SCD and FADS2 expression in pan-cancer was evaluated using GEPIA database." (PMID 38905386, 2024). "This connection becomes more relevant in conditions like cancer and neurodegenerative disorders, where FADS2's interaction with altered lipid profiles and oxidative stress aligns with the initiation of ferroptosis." (PMID 39679976, 2024). "FADS2 dysregulation at the 11q13 major cancer hotspot region alters fatty acid metabolism in several cancer types." (PMID 38672672, 2024). "Changes in phospholipid metabolism have been described in many cancers, with FADS2 expression levels altered in some cancer types, such as lung, kidney, and colon cancers." (PMID 38830851, 2024). "The tumor microenvironment is widely affected by immune-related cell infiltration, so the importance of FADS2 expression in pan-cancer immune infiltration analysis was further investigated." (PMID 36788618, 2023). "FADS2 expression was increased in both mRNA and protein and was associated with a worse OS and DFS in cancer patients." (PMID 36788618, 2023). "To compensate for this and to make the conclusion more credible now, we performed a comprehensive analysis of proteomics and transcriptomics (bulk and single-cell sequencing) to validate the role of FADS2 in cancers." (PMID 36788618, 2023). "Through the results of Gene Ontology and KEGG enrichment analysis, FADS2 plays an oncogenic driver role by driving cancer cells proliferation, cell migration, and EMT through VEGF, MAPK, and PPAR pathways." (PMID 36788618, 2023). "Studies in GBM models show that FADS2 expression is higher in GBM cancer stem cells than in other GBM cancer cells." (PMID 36765904, 2023). "In summary, this study revealed FADS2's role in the tumor immune microenvironment and its prognostic value for numerous cancers." (PMID 36788618, 2023). "FADS2 can serve as a potential prognostic and immunotherapeutic biomarker for multiple tumors, revealing new insights and evidence for cancer treatment." (PMID 36788618, 2023). "In this study, FADS2 was analyzed extensively in pan-cancer to determine its prognostic value and potential immunotherapy value." (PMID 36788618, 2023). "Recently, scientists have taken a new look at FADS2, also known as D6D, which was exploited to produce n-10 isomers in carcinoma, illustrating heterogeneity in FA desaturation and making it more plastic in signaling networks." (PMID 36951803, 2023).
cancer (continued). "One report noted that some cancer cells are able to utilize Δ6 desaturase (FADS2) to produce cis-6-C16:1 (FA 16:1; sapienate), which differs from palmitoleic acid in the location of the double bond." (PMID 36010592, 2022). "The aberrantly low levels and activation of FADS2 are closely related with cancer onset, progression and metastasis through inhibiting Ferroptosis." (PMID 35818395, 2022). "The gene expression levels of FASN, SCD and FADS2 were highly heterogeneous in GBM cancer cells and correlated with cell fate." (PMID 36338708, 2022). "Concisely, the mRNA and protein expression level of FASN and FADS2 was upregulated in ZEB1 overexpression cancer cells, while downregulated in the ZEB1-S555A mutant cells." (PMID 35844792, 2022). "In contrast, pharmaceutical inhibition and genetic ablation of SCD1/FADS2 retarded tumor growth, cancer stem cell (CSC) formation and reduced platinum resistance." (PMID 35547771, 2022). "FADS2 is overexpressed in cancer and functions as a potential oncogene that facilitates cancer cell proliferation." (PMID 35866375, 2022). "Several cancers have been validated to utilize FADS2 to desaturate palmitate to the unusual fatty acid sapienate, which can be applied to the biosynthesis of the membrane." (PMID 35433683, 2022). "FADS2 is abnormally expressed in many malignant tumors, and its expression is significantly correlated with tumor proliferation, cell migration invasion, and ferroptosis." (PMID 34422642, 2021). "These specific cancer types are insensitive to pharmacological inhibition of SCD as they upregulate delta-6 desaturase (FADS2) to produce the monounsaturated fatty acyl-CoA sapienyl-CoA (C16:1, n-10) instead of palmitoleoyl-CoA (C16:1, n-9) from palmitoyl-CoA." (PMID 33413672, 2021). "Monounsaturated sapienate, mediated by FADS2, is identified as an essential fatty acid that promotes cancer migration." (PMID 37849907, 2021). "The expression level of fatty acid desaturase 2 (FADS2), an enzyme converting palmitate to sapienate, correlated with the independence of cancer cells from SCD." (PMID 31284458, 2019). "FADS2 is aberrantly overexpressed in several cancers, including ovarian, prostate and lung cancers." (PMID 40682485, 2025). "We focused our study on SCD1 and FADS2 due to their co-implication in cancer etiology." (PMID 40403013, 2025). "A secondary objective was to examine genetically determined fatty acid profiles—shaped by FADS1 and FADS2 polymorphisms—in cancer patients without intervention and their potential association with PUFA-related cancer risk." (PMID 40430008, 2025). "Pan‐cancer analysis revealed that FADS2 was highly expressed in most cancers." (PMID 40682485, 2025). "A recent publication underscored critical importance of desaturation for cancer cells that exploits a metabolic rewiring process and engages an alternative fatty acid desaturation pathway using the fatty acid desaturase 2 (FADS2) enzyme instead of the conventional desaturation by SCD." (PMID 39337514, 2024). "Thus, combination therapy with SCD1 inhibition and FADS2 inhibition is potentially a new cancer therapeutic strategy targeting fatty acid metabolism." (PMID 38849435, 2024). "Furthermore, genetic depletion using siRNA showed that FADS2 is a key determinant of sensitivity/resistance of cancer cells to SCD1 inhibitor." (PMID 38849435, 2024). "Now, we demonstrated that treatment of PCC-cancer-derived cell lines with a polyamine analogue inhibitor DENSPM results in a broad downregulation of gene expression associated with fatty acid synthesis and processing, including FASN, SCD1, FADS2, and SREBPs." (PMID 39337514, 2024).